PIN1 (peptidylprolyl cis/trans isomerase, NIMA-interacting 1)
Diseases named in the same sentence as PIN1 in open-access papers (continued):
Sharing a sentence is not in itself a finding about the gene and the disease.
breast carcinoma (continued). "ATRA-induced Pin1 degradation inhibited the growth of HCC cells, although at a higher IC50 as compared with breast cancer cells, likely due to more active ATRA metabolism in liver cells." (PMID 28262728, 2017). "We next stained serial sections of the second group (38 TNBC samples) of breast cancer tissues with anti-N1-ICD, anti-Pin1 and anti-Fbxw7 antibodies." (PMID 24357640, 2014). "Indeed, among Notch targets several are also Pin1 substrates (e.g. cyclin D1, NF-κB, Survivin), suggesting that in addition to its role in sustaining Notch1 protein levels, Pin1 could promote breast cancer aggressiveness also by enhancing the activity of some Notch-induced Pin1 targets." (PMID 24357640, 2014). "Furthermore, SENP1 was reported to enhance PIN1 activity via deSUMOylation in breast cancer, suggesting a potential regulatory axis involving SENP1, PIN1, and the HBx protein in HCC that remains to be elucidated." (PMID 41438340, 2026). "Furthermore, PIN1 knockdown in breast cancer cells resulted in a decrease in NRF2 protein levels and activity, indicating that PIN1 is required for the stability and activation of NRF215." (PMID 40087364, 2025). "In addition, the synergistic targeting of Pin1 by ATO and ATRA is an attractive approach for combating breast cancer and other cancers." (PMID 39897037, 2025). "Moreover, the studies on breast cancer cells highlighted that H-Ras induces an interaction between NRF2 and PIN1 leading to increased expression of genes involved in antioxidant defence and cancer progression." (PMID 40087364, 2025). "Pin1 promotes tumorigenesis by stabilizing YAP and TAZ, as well as by promoting their nuclear localization and transactivation, resulting in increased drug resistance and tumorigenicity in a breast cancer model." (PMID 38727267, 2024). "In that study, DAPK1 was shown to inhibit the centrosome amplification and cell transformation of cancer cells, and a negative correlation was demonstrated with Pin1, which is an oncogene in breast cancer." (PMID 39057063, 2024). "We found a significant correlation between elevated levels of PIN1 protein, but not mRNA, and poor prognosis in breast cancer (BC) patients, irrespective of age, estrogen receptor (ER) status and tumor grade." (PMID 38622115, 2024). "The inhibition of Pin1 removes BRCA1-mediated radio resistance and homologous recombination repair mechanisms, sensitizing breast cancer cells to radiation and PARP inhibitor treatments, which both induce stress and DNA damage that the cells can no longer fully alleviate." (PMID 38727267, 2024). "Our results have indicated that silencing of NONO inhibits the PIN1 expression thereby inhibiting the CSC formation in breast cancer." (PMID 37370134, 2023). "Pin1 inhibitors such as all-trans retinoic acid (ATRA) and KPT-6566 showed a dampening of Pin1-dependent oncogenic phenotypes and growth in vivo, as well as curbed self-renewal capabilities of breast cancer stem cells." (PMID 36923534, 2023). "Since the expression of NONO protein was upregulated in human breast cancer tissues and its binding with PIN1 promotes its stability." (PMID 37370134, 2023). "Here we report that non-POU domain-containing octamer-binding (NONO) protein is overexpressed in breast cancer and validated the interaction of the WW domain of PIN1 with c-terminal threonine-proline (thr-pro) motifs of NONO." (PMID 37370134, 2023). "The data of this study showed that the Pin1 overexpression rate in DCIS (21/30, 70%) and IDC (44/80, 55%) groups was significantly higher than that in the Normal group (7/30, 23.3%), indicating that Pin1 is overexpressed in human breast cancer tissues." (PMID 37833434, 2023). "Next, we performed the IHC to examine the expression of the PIN1 protein in the same groups of human breast cancer sections in which IHC NONO was carried out." (PMID 37370134, 2023). "We found that Pin1 and TAZ were overexpressed in breast cancer than those in normal tissues." (PMID 35450041, 2022).
breast carcinoma (continued). "Next, we analyzed the expression of Pin1 and TAZ in breast cancer subtypes and pathological stage." (PMID 35450041, 2022). "In breast cancer cells, ATO may be included in Notch-1, PIN1, and kinases oncogenic signaling pathways." (PMID 36619302, 2022). "Pin1 was highly expressed in HER2+ breast cancer, but out of expect, GRB7 was still stable without over-degradation." (PMID 34980129, 2022). "Saeidiet al. reported that PIN1 could stabilize and constitutively activate NRF2 by competing with Keap1 for Nrf2 binding in breast cancer." (PMID 35983979, 2022). "Additionally, NOTCH signaling drives metastasis in numerous cancers and Pin1 prevents NOTCH1 and NOTCH4 from undergoing FBXW7-mediated degradation, leading to an increase in breast cancer stem cells’ (CSCs) self-renewal and metastasis." (PMID 33807199, 2021). "Overexpression of PIN1 increases the PTOV1 expression as a novel interactome of PIN1, and knockdown of both genes inhibits the expression of β-catenin, cyclin D1, and c-Myc in breast cancer MDA-MB-231 cells." (PMID 32258027, 2020). "Pin1 recognizes four phosphorylated Ser/Thr-Pro motifs in RUNX3 via its WW domain to suppress the transcriptional activity of RUNX3 and induce the ubiquitination and proteasomal degradation of RUNX3 in breast cancer." (PMID 32296699, 2020). "Overexpression of PIN1 converts normal human breast epithelial cells to cells with stem-like and EMT phenotypes, whereas PIN1 silencing reduces the tumorigenesis and self-renewal activity of breast CSCs in primary breast cancer tissue." (PMID 32258027, 2020). "In breast cancer tissues, the levels of Pin1 phosphorylated at Ser138 are significantly upregulated, indicating that targeting MLK3 or Pin1 Ser138 might benefit cancer treatment." (PMID 32195254, 2020). "Future combination therapy which can target both Pin1 and YAP/TAZ might be a successful strategy for the treatment of drug resistance and tumorigenesis of breast cancer." (PMID 31015482, 2019). "ATRA-induced Pin1 degradation decreased the protein stability and transcription activity of ERα, as well as reduced the phosphorylation of pro-survival kinases AKT and ERK1/2 in tamoxifen-resistant breast cancer cells." (PMID 31867329, 2019). "We found that both Pin1 protein and mRNA were up-regulated in tamoxifen-resistant MCF-7 (MCF-7R) and T47D (T47DR) cells, comparing to parental cells, which was consistent with previous reports that Pin1 was overexpressed in TAMR human breast cancer tissues." (PMID 31867329, 2019). "Moreover, targeting Pin1 by ATRA inhibited cell growth in vitro, and exhibited anti-tumor effects in vivo against tamoxifen-resistant breast cancer." (PMID 31867329, 2019). "Indeed, Pin1 knockout in NOTCH3-dependent T-ALL, Eμ-myc lymphomas, or in MMTV-Ras/neu mammary tumors in mice curbs tumorigenesis." (PMID 30873382, 2019). "Since ATRA inhibits APL, AML, breast cancer, and liver cancer by targeting Pin124,40–43, we wondered whether ATO has any effects on Pin1." (PMID 30093655, 2018). "We therefore investigated their expression patterns in sporadic TCGA breast cancer cases and, consistent with our hypothesis, observed an inverse correlation between BRCA1 and PIN1 expression levels." (PMID 30590041, 2018). "In breast cancer stem cells, high levels of prolyl-isomerase Pin1 sustain Notch signaling protecting Notch1 and Notch4 from proteasomal degradation." (PMID 30478302, 2018). "Moreover, Pin1 can also stabilize NOTCH1 expression by reducing ubiquitin ligase FBW7 to promote self-renewal and metastasis in breast cancer CSCs." (PMID 29848341, 2018). "Moreover, Pin1 knockout mice develop normally but are highly resistance to Ras, Neu/HER2 induced breast cancer or Myc-induced Burkitt’s lymphoma." (PMID 28404959, 2017).
breast carcinoma (continued). "Additionally the authors confirmed Cys113 adducts in the Pin1 active site in MDA-MB-231 breast cancer cells treated with tagged HNE (8-alkynyl-HNE) and showed that knockdown of Pin1 in MDA-MB-231 cells partially protected the cells from HNE-induced toxicity." (PMID 26437435, 2015). "Suppression of Pin1 holds promise in reverting aggressive phenotypes, through CSC exhaustion as well as recovered drug sensitivity carrying relevant implications for therapy of breast cancers." (PMID 24357640, 2014). "Pin1 controls CSC self-renewal, replicative potential and frequency by antagonizing the negative effect of Fbxw7α E3 ubiquitin-ligase on the Notch receptor pathway, a fundamental regulator of cell fate frequently subverted in breast cancer." (PMID 24357640, 2014). "While over-expression of ErbB2 or Ras is sufficient to initiate breast cancer in female mice, cancer initiation is completely blocked in Pin1−/− mice, an effect that appears to be mediated via negative regulation of cyclin D1 levels by Pin1." (PMID 24416409, 2014). "Our findings provide new insights unveiling a mechanism centered on phosphorylation-dependent prolyl-isomerization by Pin1 as responsible for sustained Notch signaling in breast cancer cells, regardless of Fbxw7α status." (PMID 24357640, 2014). "Similarly, pharmacological Pin1 inhibition shrunk mammosphere forming efficiency in a dose dependent manner in MDA-MB-231 and other breast cancer cell lines (BT-549 and SUM-159)." (PMID 24357640, 2014). "In human breast cancers, despite Fbxw7α expression, high levels of Pin1 sustain Notch signaling, which correlates with poor prognosis." (PMID 24357640, 2014). "NOP6 mouse mammary tumor cells, harboring the Her2/Neu amplification, were grown as mammospheres in presence or absence of the Pin1 inhibitor." (PMID 24357640, 2014). "In summary, we found that Pin1-inhibition sensitized Her2-positive breast cancer cells to the mTOR-inhibitor Rapamycin, but not to the direct erbB2 inhibitor Trastuzumab." (PMID 19077306, 2008). "While Pin1-inhibition greatly increased the sensitivity of Her2-positive breast cancer cells to the mTOR inhibitor Rapamycin, it did not increase their sensitivity to Trastuzumab." (PMID 19077306, 2008). "Statistical analyses further revealed a significant correlation (Spearman’s Rank Correlation (rs) = 0.4645, P = 0.01) between PIN1 and NONO in human breast cancer tissues, indicating that binding of PIN1 to NONO is involved in the oncogenic behavior of breast cancer cells." (PMID 37370134, 2023). "Although our study pointed out that TPL2 and Pin1 may synergistically promote the occurrence of breast cancer, the specific mechanisms of action have not yet been elucidated." (PMID 37833434, 2023). "Pin1 is also overexpressed in most tumors with high TPL2 expression, suggesting that TPL2 and Pin1 may synergistically promote the occurrence and development of breast cancer." (PMID 37833434, 2023). "Furthermore, to understand the role of PIN1 in the IL-34-induced MAPK pathway in breast cancer, we transfected the cells with mock and Xpress-PIN1 or siRNA-control and siRNA-PIN1, followed by treatment with or without IL-34 in MCF7 cells." (PMID 33800170, 2021). "Interestingly, there is typically high expression of both Pin1 and HER2 in most breast cancers." (PMID 33807199, 2021). "Moreover, the results of this study present PIN1 as an attractive therapeutic target in the TME, inhibition of which could potentially attenuate the aggressiveness of breast cancer." (PMID 33800170, 2021).
breast carcinoma (continued). "Over the past two decades, diverse small-molecule Pin1 inhibitors were developed and some of them, such as ATRA, KPT-6566, arsenic trioxide, and API-1, exhibited attractive in vitro and in vivo activity toward human cancer, including acute PML, breast cancer, and hepatocellular carcinoma." (PMID 32296699, 2020). "Therefore, Pin1-mediated protein degradation might partially account for the decreased RUNX3 expression, an early event in breast cancer progression." (PMID 32266261, 2020). "Pin1 participates in a variety of processes, including cell proliferation, growth suppressor evasion, genome instability and centrosome amplification, and Pin1 acts on its substrates cyclin D1, AKT, ERα, β-catenin, NF-κB, and c-MYC at the tumour initiation stage in breast cancer." (PMID 32010480, 2020). "Besides, the high expression of Pin1 and HER2 are concurrent in most breast cancers." (PMID 30158600, 2018). "While Pin1 levels did not affect the clinical outcome in all patients, we found that in grade 3 breast cancer high Pin1 levels correlate with a worse outcome in patients with activated Notch1 signature (high NDT-high PIN1), but not in patients with low NDT signature expression." (PMID 24357640, 2014). "However, although these studies showed that the absence of Pin1 prevented breast cancer induced by Her2 or Ras, they have not demonstrated that Pin1 inhibition can successfully treat breast cancer." (PMID 19077306, 2008). "Pin1 inhibition greatly increased the sensitivity of Her2-positive breast cancer cells to the mTOR inhibitor Rapamycin, while it did not increase their sensitivity to Trastuzumab, suggesting that Pin1 might act on Her2 signaling." (PMID 19077306, 2008). "Because of these kinetics, the siRNA inhibition likely mimics a pharmacological inhibition of Pin1 better than the genetic absence of Pin1, and our results indicate that siRNA inhibition of Pin1 is highly effective in inhibiting tumor cell growth of Her2+ breast cancer cells." (PMID 19077306, 2008). "Furthermore, it was found that mja-miR-35-3p could target and decrease the upregulated peptidylprolyl cis/trans isomerase NIMA-interacting 1 (PIN1) in human melanoma and breast cancer stem cells, thereby leading to the elimination of the stemness of tumor stem cells." (PMID 36532760, 2022). "Interestingly, the results showed that knockout of Pin1 decreases the cell viability as compared to their corresponding control cells, suggesting that Pin1 might cooperate with YAP/TAZ to induce Taxol resistance of breast cancer cells." (PMID 31015482, 2019). "Given our findings that BRCA1 loss results in PIN1 upregulation, we hypothesized that even in sporadic breast cancers not linked to germline BRCA1 mutation but that have low BRCA1 levels through other mechanisms, levels of BRCA1 and PIN1 expression would be inversely correlated." (PMID 30590041, 2018). "Moreover, Pin1 functions as an essential protein required for angiogenesis, EMT-like behavior and migration/invasion of cancer cells, all of which may contribute to the metastatic ability of TAM-resistant breast cancer." (PMID 29050342, 2017). "RT-qPCR and Western blot analysis showed that NONO silencing significantly reduced PIN1 mRNA and protein levels suggesting that PIN1, indicating that NONO promotes CSC-like properties in breast cancer cells via regulation of PIN1 expression." (PMID 37370134, 2023).
breast carcinoma (continued). "In this study, we identified PIN1 as a positive regulator of NONO and characterized the downstream targets of NONO that drive the breast cancer progression." (PMID 37370134, 2023). "Although our data demonstrated that ATRA targeted Pin1 to promote ERα protein degradation, decrease ERα transcriptional activity, and inhibit AKT and ERK1/2 pathway, the therapeutic potential of ATRA in treating tamoxifen-resistant breast cancer was still not clear." (PMID 31867329, 2019).